CACYBP (calcyclin binding protein)
Diseases named in the same sentence as CACYBP in open-access papers (continued):
Sharing a sentence is not in itself a finding about the gene and the disease.
kidney cancer (1 paper, 2023). Primary or metastatic malignant neoplasm involving the kidney. "CacyBP/SIP inhibited the proliferation of kidney cancer cells by affecting the expression of β-catenin." (PMID 37373509, 2023). "One study showed that CacyBP/SIP, by lowering the level of β-catenin, inhibited the proliferation of kidney cancer." (PMID 37373509, 2023).
lung fibrosis (1 paper, 2024). "To compare the differences in CACYBP expression between the two lung fibrosis groups, we conducted immunohistochemistry, H&E, and Sirius red staining of FFPE lung tissue samples from the three groups." (PMID 39301288, 2024).
Parkinson disease (1 paper, 2020). A progressive degenerative disorder of the central nervous system characterized by loss of dopamine producing neurons in the substantia nigra and the presence of Lewy bodies in the substantia nigra and locus coeruleus. "In the present work, we have analyzed the influence of CacyBP/SIP on aggregation of α-synuclein, a protein present in Lewy bodies of Parkinson’s disease brain." (PMID 33049998, 2020).
renovascular hypertension (1 paper, 2024). High blood pressure secondary to renal artery stenosis. "In the adrenal medulla of SHR rats, the CacyBP/SIP‐immunoreaction was very weak, while in the group of rats with renovascular hypertension, it was clearly visible in some cells." (PMID 38780511, 2024).
Right ventricular hypertrophy (1 paper, 2022). In this case the right ventricle is more muscular than normal, causing a characteristic boot-shaped (coeur-en-sabot) appearance as seen on anterior- posterior chest x-rays. "Moreover, after inhibition of CacyBP/SIP expression in vivo, we observed increased right ventricular hypertrophy index, poor hemodynamics, and severe vascular remodeling." (PMID 36042446, 2022).
secondary hypertension (1 paper, 2023). High blood pressure caused by an underlying medical condition. "In summary, we have provided the first evidence linking CacyBP/SIP to ERK1/2 and p38 kinase in the adrenal gland in experimental models of primary and secondary hypertension." (PMID 38203261, 2023).
synucleinopathies (1 paper, 2020). "Continuation of this work may point to CacyBP/SIP as a potent factor able to attenuate α-synuclein pathology and may create basis for development of new therapeutic strategies applicable in treatment of PD and other synucleinopathies." (PMID 33049998, 2020).
tumor (29 papers, 2012 to 2026). "Our findings revealed that elevated CACYBP expression in LUAD is associated with advanced neoplasia and poor prognosis." (PMID 40167359, 2025). "In vitro and in vivo assays were used to investigate the regulation of CacyBP on tumor-associated macrophages (TAMs)." (PMID 37968706, 2023). "Among the signature genes we researched, HSPA4, FABP6, S100A10, CACYBP, SHC1 and HDAC1 were associated with a higher tumor grade, CACYBP was linked with a higher clinical stage as well as T stage." (PMID 32191631, 2020). "Interestingly, it was observed that risk signatures could accurately reflect tumor grade characteristics and the expression level of CACYBP is also correlated with grade (p < 0.05)." (PMID 37077914, 2023). "Through analysis of RNA-seq count data from the TCGA-LUAD cohort, the CACYBP gene (ENSG00000116161) was found to be significantly upregulated in tumor samples compared to normal tissues (log2FC ═ 0.862, P ═ 3.99 × 10−24)." (PMID 40167359, 2025). "In conclusion, CACYBP appears to function as a tumor promoter in LUAD, at least in part through CDK1-mediated activation of the PI3K/AKT pathway." (PMID 40167359, 2025). "These individuals were divided into low-expression and high-expression groups based on the median CACYBP gene expression levels in tumor samples." (PMID 40167359, 2025). "Results from both the overall cohort and a subset of 57 paired samples demonstrated that CACYBP mRNA expression was significantly higher in tumor tissues than in normal tissues." (PMID 40167359, 2025). "In consistence with our previous findings, inhibition of CacyBP impaired tumor growth and decreased tumor infiltration of F4/80+CD163+ macrophages." (PMID 37968706, 2023). "In order to clarify the role of CACYBP in the development and progression of PC, the expression of CACYBP in 87 tumor tissues and 45 para-carcinoma tissues was detected by IHC analysis." (PMID 36576589, 2023). "In agreement with tumor volume, tumor weight also showed a remarkable reduction when CACYBP was silenced (p < 0.05)." (PMID 37305391, 2023). "The biological roles of CACYBP on proliferation, apoptosis, cycle distribution, migration and tumor formation of PC were investigated by Celigo cell counting assay, flow cytometry, transwell assay, wound-healing assay and mice xenograft models, respectively." (PMID 36576589, 2023). "The upregulation of CACYBP has been reported to promote tumor progression and lead to significantly worse OS in various cancers." (PMID 37298537, 2023). "CACYBP knockdown inhibited the proliferation and migration of PC cells in vitro and suppressed the tumor growth in vivo." (PMID 36576589, 2023). "In vivo experiment further verified the inhibitory effect of CACYBP knockdown on tumor growth of PC." (PMID 36576589, 2023). "A number of studies, including our own one, have identified that CacyBP as an independent risk factor for HCC and it is critical for tumor growth and proliferation." (PMID 37968706, 2023). "SIP, also called CacyBP, was first discovered in mouse tumor cells as a target of S100A6 (calcyclin) protein." (PMID 35305696, 2022). "As highlighted in current studies, CACYBP promotes tumor occurrence and progression in various tumors via anti-apoptotic activity in cancer cells and inhibiting the cell cycle." (PMID 35356506, 2022). "The results showed that CacyBP was significantly upregulated in tumor tissues compared to normal tissues." (PMID 34179100, 2021). "Although we highlight the roles of some sIFRGs in indicating prognosis and verified the expression level of CACYBP in cell lines and tumor tissues, some limitations remain to be further discussed." (PMID 32570217, 2020). "A weak but statistically significant negative association was observed when performing correlation analysis using expression scores of RNF41 and CACYBP in HCC tumor tissues." (PMID 31754404, 2019).
tumor (continued). "The MTT assay, FACS assay, clonogenic assay and tumor xenograft experiment were performed to assess the effect of CacyBP/SIP on cell growth and tumorigenesis in vitro and in vivo." (PMID 22295074, 2012). "Previous studies have demonstrated that CACYBP plays diverse roles in tumor development." (PMID 40167359, 2025). "Our results also showed that high CACYBP expression correlates with advanced neoplasia and poor prognosis, suggesting its potential as a predictive biomarker for identifying high-risk LUAD patients who may benefit from more aggressive treatment." (PMID 40167359, 2025). "Moreover, our data demonstrate that CACYBP knockdown suppresses tumor growth in both in vitro and in vivo models, highlighting its potential as a therapeutic target." (PMID 40167359, 2025). "Gene expression levels of CACYBP in tumor vs normal tissues were assessed using a t-test." (PMID 40167359, 2025). "Moreover, its expression correlated with tumor stage, and patients with high CACYBP expression exhibited poorer survival outcomes." (PMID 40167359, 2025). "Moreover, CACYBP overexpression was markedly related to the characteristics of tumor grade and recurrence of state." (PMID 37305391, 2023). "CACYBP exerted a tumor-promoting role in CCA by suppressing ubiquitination of MCM2 and activating Wnt/β-catenin pathway, hence revealing that it may be the possible therapeutic target for CCA treatment." (PMID 37305391, 2023). "Moreover, by using in vitro and in vivo strategies, we demonstrated that depletion of CacyBP impaired the infiltration of TAMs and the immunosuppressive state of the tumor microenvironment, further sensitizing HCC-bearing anti-PD-1 therapy." (PMID 37968706, 2023). "Subsequently, this work conducted in-vivo assays for assessing CACYBP’s effect on tumor formation." (PMID 37305391, 2023). "CACYBP knockdown significantly attenuated tumor formation in mice (p < 0.01)." (PMID 37305391, 2023). "In addition, in contrast to the tumor-promoting role of CacyBP, Siah-1 expression tended to be downregulated in HCC tissues, and patients with reduced Siah-1 expression showed a lower OS and disease-free survival (DFS)." (PMID 37968706, 2023). "In contrast, in tumor-bearing tissues, the level of CacyBP/SIP was significantly elevated." (PMID 37373509, 2023). "Furthermore, the tumor tissue of patients with advanced PC was more abundant in CACYBP than that of patients with early PC, suggesting that the expression of CACYBP in PC was positively correlated with pathological grade." (PMID 36576589, 2023). "Therefore, targeting CacyBP can not only inhibit the growth of tumor itself, but also extend the current approaches of anti-PD-1-based immunotherapy." (PMID 37968706, 2023). "Because of the cancer-prone environment and property, CACYBP expression may have a lower but detectable level in tumor adjacent tissues and immortalized hepatic cell lines." (PMID 31754404, 2019). "However, in normal hepatic cells, RNF41 promotes the degradation of CACYBP via E3 ligase activity and counteracts its tumor-promoting effect." (PMID 31754404, 2019). "CACYBP protein also showed an upregulated pattern in the tumor sections among these samples." (PMID 31754404, 2019). "Particularly in HCC, CACYBP expression was 1.9-fold higher in tumor compared to normal tissues." (PMID 31754404, 2019). "CACYBP is up-regulated in tumor tissue, as compared to normal tissue." (PMID 28163897, 2016). "Additionally, CACYBP expression was upregulated in tumor tissues in ten paired LUAD samples." (PMID 40167359, 2025). "In addition, CACYBP knockdown weakened the tumor growth of PC in vivo." (PMID 36576589, 2023). "Notably, CACYBP was also required for tumor formation in mice." (PMID 37305391, 2023). "In addition, it should be taken into account that various CacyBP/SIP ligands are involved in carcinogenesis and interactions of CacyBP/SIP with other proteins may inhibit or promote tumor cell proliferation." (PMID 37373509, 2023).
tumor (continued). "Similarly, our results indicated that RNF41 may also act as a tumor suppressor by degrading CACYBP in HCC." (PMID 31754404, 2019). "Moreover, CACYBP exerts its tumor-promoting effect by releasing rapid cell cycle progression through promoting the Ser10 phosphorylation and subsequent cytoplasmic sequestration of P27Kip1, whereas RNF41 could act against CACYBP function in HCC." (PMID 31754404, 2019). "Taking gastric cancer as an example, CacyBP/SIP can inhibit the proliferation of tumor cells, reduce the invasion ability, and prolong the survival of tumor-bearing mice." (PMID 34179100, 2021). "In summary, we provide evidence that overexpression of CACYBP in HCC inhibits the cell cycle-restricted role of P27Kip1 and enhances tumor progression." (PMID 31754404, 2019). "To better understand the role of CacyBP/SIP in breast cancer, particularly during its development, we used a rat model of this tumor." (PMID 22926504, 2014). "The expression of CACYBP was evaluated in ten pairs of LUAD carcinomas and adjacent tissues, and it was found that CACYBP was significantly highly expressed in the tumor tissues, which was similarly validated in our cell line experiments." (PMID 36776843, 2023). "Moreover, by analyzing relationship of CACYBP level with tumor features in CCA patients, CACYBP overexpression showed positive relation to T stage, tumor grade and recurrence of state (p < 0.05), as confirmed through Pearson correlation analysis." (PMID 37305391, 2023). "In addition, CACYBP silencing inhibited oncogenic features in CCA cell lines and suppressed tumor formation in mice." (PMID 37305391, 2023). "To further verify the relevance of IFRGs to tumor characteristics and the indicating effects, we analyzed and assessed the expression levels of CACYBP in a non-BCa population and patients with BCa with various T-stages at the genetic and protein levels." (PMID 32570217, 2020). "In some tumor cells, CacyBP/SIP has been shown to be involved in cell apoptosis, but the promotion or suppression of cancer apoptosis by CacyBP/SIP may depend on cell type." (PMID 30234028, 2018). "However, the possible impact of CacyBP on the tumor immune microenvironment has not yet been clarified." (PMID 37968706, 2023). "A positive immunohistochemical reaction for WNT10A, Fzd5, β-catenin, GSK-3ß, CacyBP/SIP, and LMP7 was observed in all studied kidneys tissues, although the intensity of immunoreaction varied between non-malignant kidney and RCC tissue samples, depending on the histological type of the tumor." (PMID 33330038, 2020). "However, we observed no tumor formation even at month 2 after subcutaneously injecting either LO2 control or CACYBP-overexpressing cells into NSI mice (data not shown)." (PMID 31754404, 2019).
cancer (26 papers, 2012 to 2025). A tumor composed of atypical neoplastic, often pleomorphic cells that invade other tissues. "Calcyclin-binding protein (CACYBP) is a multidomain adaptor protein implicated in the development of various cancers." (PMID 40167359, 2025). "Although literatures have revealed overexpression of CacyBP in many cancers and its association with poor prognosis, the impact of CacyBP expression on the immune microenvironment, especially on regulating TAMs, remains poorly defined." (PMID 37968706, 2023). "Accordingly, MCM2 up-regulation partly reversed CACYBP deficiency’s inhibition against cancer cell viability and invasion." (PMID 37305391, 2023). "Calcyclin-binding protein (CACYBP) is a multi-ligand protein implicated in the progression of various human cancers." (PMID 31754404, 2019). "CACYBP is linked to the G checkpoint of the cell cycle and is associated with cancer immunotherapy." (PMID 39033098, 2024). "CACYBP is a multi-ligand protein implicated in the progression of various human cancers." (PMID 36576589, 2023). "Although CACYBP overexpression is associated with the development of these types of cancers, its effect on CCAs is still unknown." (PMID 37305391, 2023). "Research studies have shown changes in the level and activity of CacyBP/SIP in several cancers of various organs." (PMID 37373509, 2023). "Since β-catenin plays an important role in processes related to proliferation and tumorigenesis, it can be assumed that CacyBP/SIP regulates the proliferation of cancer cells by affecting the SCFTBL1 complex." (PMID 37373509, 2023). "CacyBP/SIP levels are altered in several cancers, indicating its involvement in maintaining cellular homeostasis." (PMID 37373509, 2023). "The results revealed that high expression of CACYBP was mainly found in the PC, while low expression was present in para-carcinoma tissues." (PMID 36576589, 2023). "Herein, CACYBP showed high expression within human CCA in comparison with non-carcinoma tissues, in line with the data from TCGA." (PMID 37305391, 2023). "It has been shown that CacyBP/SIP can act as a tumor suppressor or an oncogen depending on the type of cancer." (PMID 33330038, 2020). "Forced overexpression of CacyBP/SIP in RCC cell lines has been shown to reduce the proliferative potential of cancer cells in vitro and their carcinogenicity when injected into mice." (PMID 33330038, 2020). "Independent scientific centers have indicated the importance of CacyBP/SIP in the process of cancer formation." (PMID 33330038, 2020). "To obtain a whole picture of CACYBP expression in human malignancy, we first searched the TCGA database and found that CACYBP mRNA expression was high in cancer tissues from most of the listed cancer types." (PMID 31754404, 2019). "Possible involvement of CacyBP/SIP in many cancers, including gastric, breast, pancreatic, colorectal, brain and renal has also been proposed." (PMID 28283909, 2017). "We found that the level of CacyBP/SIP increases during development of cancer in a manner similar to the level of an oncogene, β-catenin." (PMID 22926504, 2014). "The observed discrepancies in CACYBP’s role across different cancers may be attributed to specific cellular contexts and the involvement of distinct molecular pathways." (PMID 40167359, 2025). "CACYBP had an important effect on in-vitro and in-vivo cancer cell proliferation and migration." (PMID 37305391, 2023). "CACYCLIN binding protein (CACYBP) is involved in the progression of a variety of cancers." (PMID 36576589, 2023). "Calcyclin-binding protein (CACYBP) shows aberrant expression within several malignant tumors, but the role of CACYBP in CCA remains unknown." (PMID 37305391, 2023). "Furthermore, previous articles suggest that CACYBP promotes the development of several cancer types." (PMID 37305391, 2023). "However, the tissues obtained from cancer patients were merely used for preliminary exploration of CacyBP/SIP expression with IHC and IF." (PMID 36042446, 2022).
cancer (continued). "We also tested whether knockdown of CacyBP expression with siRNA affects the ability of gastrin to stimulate proliferation of cancer cells." (PMID 28196083, 2017). "Furthermore, CACYBP may play a role in tumorigenesis by participating in the degradation of cancer-related proteins." (PMID 36576589, 2023). "CACYBP (calcyclin-binding protein) represents part of ubiquitin E3 complexes and participates in calcium-dependent ubiquitination and proteasomal degradation of target substrates which plays a role during the regulation of proliferation in several cancer cells." (PMID 32375238, 2020). "Calcyclin-binding protein (CYBP) has been reported as a migration suppressor, and cathepsin K is well known as a positive regulator of bone resorption, cancer progress, and cancer cell migration." (PMID 36674719, 2023). "A component of the ubiquitin pathway, CACYBP, is overexpressed in CRC patients and has increased cancer proliferation." (PMID 35194111, 2022). "Essential regulatory roles for CacyBP/SIP in various cancers have been determined, and CacyBP/SIP has been regarded as a potential target for cancer therapy." (PMID 36042446, 2022). "On the contrary, in sections of the mammary sample taken 6 weeks after DMBA treatment, which showed histopathological changes, the CacyBP/SIP immunoreactivity was more prominent, present in a form of deposits in the cytoplasm of cancer cells." (PMID 22926504, 2014). "In addition, CACYBP levels within CCA (n = 79) and normal para-carcinoma tissues (n = 26) of human tissue chip was observed using IHC analysis." (PMID 37305391, 2023). "Furthermore, CACYBP expression was significant difference between CCA (44.3%) and non-carcinoma tissues (3.8%) (p < 0.001)." (PMID 37305391, 2023). "So blocking the combination of S100 and CacyBP/SIP could promote β –catenin degradation, result in inhibiting the proliferation of cancer cells." (PMID 22295074, 2012).
infection (1 paper, 2019). The state of being infected such as from the introduction of a foreign agent such as serum, vaccine, antigenic substance or organism. "We also constructed CACYBP-overexpressing SK-Hep-1 and LO2 cells after infection with the lentivirus encoding Flag-tagged CACYBP." (PMID 31754404, 2019).